MMP2 (matrix metallopeptidase 2)
Diseases named in the same sentence as MMP2 in open-access papers (continued):
Sharing a sentence is not in itself a finding about the gene and the disease.
tumor (continued). "MMP2, expressed in almost all human tissues and also known as type IV collagenase, plays a key role in invasion and metastasis and is often associated with tumor development." (PMID 38678020, 2024). "The active MMP2 is implicated in cancer invasion by degrading the ECM surrounding the tumor cells." (PMID 37958410, 2023). "Furthermore, higher expression of MMP2 in tumor tissue samples was associated with shorter survival in patients with adenocarcinoma." (PMID 37509417, 2023). "Similarly, the LAP domain of TGF-ß was fused with melittin, with an MMP2 cleavage site in the middle, to create a recombinant adenovirus that encodes a tumor-activated pro-cytolytic peptide." (PMID 38133203, 2023). "The activation of CX3CL1 (chemokine C-X3-C motif ligand 1, also known as fractalkine)/CX3CR1 (CX3C chemokine receptor 1) in tumor-associated microglia/macrophages (TAMs) increases the adhesion/migration capacity of GBM cells through the expression of MMP-2, -9, and -14." (PMID 37108208, 2023). "Hence, impaired tumor-induced angiogenesis was observed in MMP-2-deficient mice, resulting in dramatically smaller tumor volumes compared to those in wild-type mice following identical tumor injections." (PMID 36768503, 2023). "Moreover, tumour invasion is often associated with the enhanced synthesis of matrix metalloproteinases (MMPs), among which MMP‐2 and MMP‐9 are of central importance." (PMID 35366056, 2022). "MMP7 is upstream of MMP9 and MMP2 that are extensively implicated in tumor metastasis." (PMID 32761892, 2022). "USP2 was associated with enhanced tumor invasiveness via modulation of MMP2 expression." (PMID 36567903, 2022). "Finally, to explore the involvement of MMP9 in angiogenic and invasive processes, we concomitantly analyzed the baseline plasma expression of five related factors implicated in the tumor microenvironment: MMP2, VEGFA, VEGFR2, CXCR4, and CXCL12." (PMID 34980260, 2022). "A study of the molecular mechanism showed that FOXP3 promotes tumor metastasis and invasion might be associated with the upregulation of MMP2 and MMP9 expression." (PMID 36235242, 2022). "Matrix metalloproteinase 2 (MMP2) can degrade most components of the extracellular matrix, and it is widely accepted that the effect of MMP2 on the extracellular matrix is closely associated with tumor invasion and metastasis." (PMID 36559076, 2022). "In addition, Zhang’s group synthesized camptothecin-encapsulated mesoporous silica nanoparticles surface functionalized with targeting cRGD and MMP-2 responsive fluorescence imaging groups, acting as a diagnostic platform as well as for tumor location." (PMID 36096856, 2022). "Such as, it has been anticipated that loss of MMP2 in GBM cells could represent a tumor escape mechanism." (PMID 35267432, 2022). "Matrix metalloproteinases are a family of extracellular endopeptidases capable of degrading all extracellular matrix components, in which MMP-1 and MMP-2 are the two major components of the family and are believed to be mainly associated with tumor invasion and metastasis." (PMID 34976177, 2022). "MMP2 and −9 deficient mice showed slowed tumor progression and metastases." (PMID 33526844, 2022). "At the same time, the study also immobilized the matrix metalloproteinase-2 (MMP-2) substrate polypeptide-linked PD-L1 inhibitor D-peptide antagonist (DPPA-1) on the outer membrane through fatty acid molecules to achieve DPPA-1 in the tumor." (PMID 36005653, 2022). "In U87 GBM xenografts expressing UII and UT in the glial and vascular compartments, UII accelerated tumor development, favored hypoxia and necrosis associated with increased proliferation (Ki67), and induced metalloproteinase (MMP)-2 and -9 expression in Nude mice." (PMID 33937253, 2021). "Finally, greater numbers of NK cells with associated granzyme B infiltrated the tumor bed in Mmp2-KO tumors." (PMID 34032639, 2021).
tumor (continued). "Thus, we performed the present meta-analysis to investigate the associations between MMP2/9 expressions in tumor cells with clinicopathologic features and survival outcome in BC patients." (PMID 33568081, 2021). "In this perspective, TRIM6 stimulates the EMT and production of MMP2, which could facilitate tumor cell migration, invasion, and metastasis, thus, causes tumor recurrence." (PMID 34589421, 2021). "Moreover, MMP-2 activity is required for the angiogenic switch during tumor development and has, together with MMP-9, been implicated in the regulation of expression and release of vascular endothelial growth factor (VEGF)." (PMID 34055644, 2021). "MMP2 has been implicated in tumor development and morphogenesis." (PMID 34646828, 2021). "The presence of MMP-2 in this scenario may potentially result in the degradation of type IV collagen, a component of the basement membrane, causing tumor invasion." (PMID 33540535, 2021). "Additionally, N-Cadherin promotes the metastatic potential of the tumor through extracellular matrix degradation processes, which increased MMP-2 and 14 expression, and the transcription of genes associated with induction of metastatic activity." (PMID 34684168, 2021). "Other groups have also shown similar associations between MMP2 and tumor progression and invasion." (PMID 34032639, 2021). "MMP-2 activity and expression are strongly associated with advanced tumor stage or poor survival." (PMID 34150657, 2021). "Similarly, in CC, an association of MMP-2 activation with αvβ3 integrin/MT1-MMP/TIMP-2 has been implicated in tumor cell migration." (PMID 35145899, 2021). "In addition, the FAK/Src and AKT pathways have previously been associated with increased tumor metastasis and upstream signaling pathways of MMP-2 expression." (PMID 34832965, 2021). "Finally, functional assays revealed that YAP overexpression stimulates OS cell migration and MMP-2/9 activity, two MMPs implicated in the tumor metastatic process such as in OS." (PMID 34765560, 2021). "MMP-2 expression has been shown to be associated with tumor aggressiveness and poor prognosis." (PMID 33999958, 2021). "This might be of importance, as not only tumor cells but also cells from the tumor microenvironment (e.g. tumor-associated macrophages (TAM)) are described to express MMP-2 and MMP-932." (PMID 32581215, 2020). "Finally, a particularly innovative approach using an oxaliplatin prodrug and a pegylated photosensitizer activated by tumor microenvironment-associated matrix metalloproteinase-2 (MMP2) showed synergy with injection of CD47 antibodies into the tumor." (PMID 35582455, 2020). "Some authors found it independently associated with lower overall survival, but others affirmed that its association with tumor progression may be due to its role in MMP-2 activation." (PMID 32669083, 2020). "Moreover, heterozygous mutant (Foxc2+/−) mice show significantly decreased expression of Vegf and Mmp2, and the haplo-deficiency of Foxc2 results even in impaired formation of tumour blood vessels as well as reduced tumour growth." (PMID 33076927, 2020). "Downregulation of MMP-2 results in loss of angiogenic potential and inhibits tumor cell migration." (PMID 33096744, 2020). "Moreover, the combined analysis of TIMP-2 with MMP-2 increased the diagnostic sensitivity up to 96%, and this value was higher than for the measurement of classical tumor markers in combination." (PMID 30719232, 2019). "In NSCLC, the MMP2 upregulation has been associated with greater tumor size or distant metastasis." (PMID 31921636, 2019). "Similarly, delphinidin also decreased the expression of matrix metalloproteinase-2 (MMP-2), a proteinase that is highly associated with tumor metastasis." (PMID 31831830, 2019). "Also, compared to WT mice, lower levels of liver markers (AST, ALT, Bil), cytokines (Tnfα, Tgfβ, Il6), and tumor markers (c-Myc, Mmp2, Epcam) in Pecam-1-deficient mice after TAA-application underline the important functions of PECAM-1." (PMID 31344919, 2019).
tumor (continued). "Tumor cells use matrix metalloproteinases 2 and 9 (MMP2 and 9) during invasion causing tumor dynamic changes; additionally, MAP2 is a major regulator of microtubule dynamics in neuronal cells and other cell types, and is associated with cell migration in epithelial cells." (PMID 30696040, 2019). "Importantly, tumor-associated macrophages (TAMs) secrete membrane-bound or soluble proteases, such as MMP-2, MMP-9, and MMP-12, which are involved in ECM degradation and promote the infiltration of tumor-associated blood vessels." (PMID 31921634, 2019). "However, according to our knowledge, little is known about diagnostic usefulness of MMP-2 in relation to its tissue inhibitor in the sera of PC patients and in comparison to well-established tumor markers, such as CA 19-9 and CEA." (PMID 30719232, 2019). "However, several studies have reported that ionizing radiation (IR) activates nuclear factor kappa B (NF-κB) that causes radioresistance and induces matrix metalloproteinase (MMP)-2/-9, which promote tumor migration and invasion." (PMID 30336548, 2018). "Nm23 inhibits molecules and signalling pathways associated with tumor invasion such as MMP-2 and the MAPK and TGF-β pathways; however, the protein interactions involved remain unclear." (PMID 30148861, 2018). "Both VEGF-A and MMP-2 are associated with tumor-related vascularization." (PMID 28388537, 2017). "We further observed that patients with wtIDH1 tumors tended to have a higher MMP-2 expression than patients with mIDH1 tumors further supporting the idea that MMP-2 contributes to tumor aggressiveness as patients with mutations in IDH have a better prognosis, especially in WHO grade II-III." (PMID 28234925, 2017). "The suggested mechanism by which Rab27b stimulates invasive tumor growth includes regulation of the heat shock HSP90α protein and the indirect induction of MMP-2, a protease that requires an association with extracellular HSP90α for its activity to accelerate the degradation of extracellular matrix." (PMID 29284484, 2017). "Given that vasculogenesis is vital for tumor growth and progression and MMP2 and MMP9 have been implicated in angiogenesis, we next tested whether Rab40b knockdown is required for primary tumor vascularization." (PMID 27789576, 2016). "MMP2 is a member of MMPs family involved tissue remodeling, degradation of collagens and interaction with other extracellular matrix macromolecules, which linked to enhanced tumor invasion/metastasis in several in vitro and in vivo model systems." (PMID 27835587, 2016). "Thus, the data suggest that grifolin effectively suppresses the enzymatic activity of MMP-2 in high metastatic tumor cells and the action is associated with ERK1/2 signaling." (PMID 27626695, 2016). "Moreover, the authors noted that the reduction in OGT expression in tumor cells was associated with decreased expression of MMP-2, MMP-9 and VEGF and blocked bone metastasis." (PMID 25315705, 2015). "The previous study certified that MMP-2 is associated with the metastasis of tumor." (PMID 26788112, 2015). "MMP-2/9 has been implicated in tumor invasion and metastasis." (PMID 25868853, 2015). "Also, it significantly suppressed PaCa cells invasion and reduced the activity of uPAR/MMP-2 signaling and Integrin/Src/Fak-mediated signaling, as integral tumor cell pathways associated with invasion, migration, adhesion, and proliferation." (PMID 25170871, 2014). "The association between HIF-1α and MMP2 expression in tumor tissues has rarely been studied." (PMID 25013467, 2014). "We hypothesized that the expression of MMP2 in the tumor microenvironment can be considered as a hallmark feature or cancers with high metastatic potential and, consequently, MMP2 cleavable peptide can be used to enhance the detection of metastases by MRI." (PMID 24919932, 2014).
tumor (continued). "Moreover, our previous study with nude mice inoculated with LM8 cells showed that decreased expression of MMP-2 within the primary tumor was associated with the suppression of the development of metastasis in the lung." (PMID 24690154, 2014). "Since MMP-2 is currently recognized as the subtype that has the best-established association with tumor malignancy, in vivo imaging of its activity should be useful for tumor diagnosis." (PMID 25010662, 2014). "Interestingly, re-expression of Foxm1 in SPDEF-deficient tumor cells restored cell migration, coinciding with elevated levels of MMP2, MMP9 and MMP13." (PMID 25254494, 2014). "Moreover, a significant finding of our study is the demonstration that downregulation of NPRA can suppress tumor invasion and migration and is associated with MMP2 and MMP9 expression." (PMID 24885858, 2014). "It was shown that the association between activity of MMP-2 in tumor and presence of DTCs in BM, in particular MMP-2 activity was 9.2 ± 5.1 μg/g tissue in patients with DTCs in BM whereas MMP-2 activity, was 4.1 ± 2.8 μg/g in patients without DTCs in BM (P < 0.05)." (PMID 24669218, 2014). "The gelatinases MMP-2/-9 are associated with EMT to increase tumour invasion and metastasis." (PMID 23378237, 2013). "We have recently reported that Songyou Yin (SYY), a mixture of five herbs inhibited HCC growth, prolonged survival by inducing tumor apoptosis associated with caspase-3 activation, and inhibited invasiveness associated with downregulation of matrix metalloproteinase-2 (MMP-2)." (PMID 23622143, 2013). "MMP-2 is largely implicated in promoting angiogenesis and tumor metastasis." (PMID 23786715, 2013). "MMP2 plays a key role in the degradation of the extra-cellular matrix, and an increase in expression has been associated with increasing tumor cell migration and tumor angiogenesis." (PMID 23072359, 2012). "Moreover, we found that at identical concentrations CA decreases the activity of important ECM-degrading proteases, as uPA, MMP-9 and MMP-2 which are closely associated with tumor progression." (PMID 22246562, 2012). "An increase of MMP-2 expression is associated with tumor invasiveness, metastasis, and prognosis." (PMID 22949882, 2012). "The presence of tumour MMP-2 expression was associated with differentiation and clinical stage." (PMID 23107277, 2012). "In an investigation of gene expression during tumor progression in the breast, it was found that extensive changes in gene expression occur in tumor-associated stroma, including increased expression of MMP2, MMP11, and MMP14 during the transition from a preinvasive to invasive phenotype." (PMID 21647291, 2011). "Invasion of tumor cells has been associated with increased expression of MMP-2." (PMID 21858102, 2011). "Disruption of caveolae activates MMP-2 in fibrosarcoma cells while Cav-1 overexpression in tumor cells causes decreased MMP-2 activity suggesting that Cav-1 may participate in the regulation of MMP-2." (PMID 20436850, 2009). "Indeed, MMP-2 overexpression has been associated not only with the invasive potential of many tumor cell lines in vitro but also with the malignant phenotype in vivo." (PMID 18426555, 2008). "Multivariate analysis against the prognosis-associated parameters gender, age and TNM classification showed that the MMP-2 SNP was independently associated with survival, whereas the tumour protein levels of MMP-2 just lost and MMP-9 completely lost their significance." (PMID 18506186, 2008). "Furthermore, PPARγ agonists reduced celladhesion, cell migration, and tumor invasion which was associated with adecrease in matrix metalloproteinase 2 (MMP2) levels." (PMID 18725982, 2008). "Our findings suggest that targeting the pathways influenced by miR-4488 or MMP2 in tumor-associated macrophages could disrupt the metabolic and immune suppression interplay between tumors and macrophages, presenting a promising therapeutic approach to combat liver metastasis." (PMID 38904015, 2024).
tumor (continued). "Moreover, upregulation of MMP-2 in tumor cells was linked to reduced disease-free survival." (PMID 38672151, 2024). "In addition to CAFs being enriched in the stromal tissue compared with normal tissue, certain subsets of tumor-associated macrophages were found to preferentially bind to CAFs and endothelial cells leading to activation of MMP2, a gene associated with tumor growth and metastasis." (PMID 36810872, 2023). "In addition, both TEM1 and MMP-2 were associated with tumor development." (PMID 36639546, 2023). "In addition, endostatin blocks the activation and activities of certain tumor-associated pro-MMPs, such as pro-MMP-2, − 9, and − 13, which may explain, at least in part, the antitumor effect of endostatin." (PMID 36419008, 2022). "In addition, the expression of MMP-2 was shown to be associated with tumor angiogenesis and VM." (PMID 36354702, 2022). "Moreover, PCP-Mn-DTA@GOx@1-MT also displayed the strongest migration and invasion suppression with coverage rates of 30.1% and 24.9%, respectively (p < 0.01), as further revealed by the expression and quantitative analysis of the tumor invasion-associated proteins (E-Cadherin, MMP2, and MMP9)." (PMID 35577812, 2022). "Interestingly, tumor ECs from metastatic tumors showed a higher invasive potential than tumor ECs from non-metastatic tumors, and this has been linked with higher expression levels of gelatinase/collagenase IV, MMP-2 and MMP-9." (PMID 34073394, 2021). "Finally, we observed that stromal factors such as IL-6 and IL1B may underlie the different effects of the involvement of MMP2-positive BMDCs in tumor invasion." (PMID 35008304, 2021). "Furthermore, SIRT1, through MMP2 regulation, is implicated in tumor metastasis." (PMID 33917352, 2021). "Moreover, enhanced MMP-9 expression in CRC cells is associated with increased invasiveness of the tumor, while levels of MMP-2 expression in CRC are lower than in adjacent normal mucosa, and significantly correlate with the depth of invasion and the presence of liver metastasis." (PMID 34071492, 2021). "Therefore, we further explored the association of MMP2/9 with the tumor–immune environment." (PMID 32988398, 2020). "Overexpression of RECK reduced cell growth and invasion and abrogated the tumour‐promoting effect and MMP‐2/‐9 expression caused by miR‐15b, which was consistent with previous studies in cancer cells 20, 33, 38 indicating that miR‐15a might promote the tumorigenicity of PCa cells via targeting RECK." (PMID 29363862, 2018). "Thus, genetic variants that influence the level of MMP2 gene expression or protein function could contribute to tumor invasion and metastasis." (PMID 29069837, 2017). "It has been shown that TβRI-ICD associates with p300 and activates genes involved with tumour invasion, such as MMP2; here, we show by knockdown of APPL proteins that the nuclear TβRI-ICD-APPL protein complex regulates MMP2 and MMP9 expression, which could promote cancer cell invasion." (PMID 26583432, 2016). "Furthermore, the expression of MMP-2 is associated with tumor invasion and metastasis." (PMID 25634589, 2015). "In addition, the degradation of the extracellular matrix (ECM) including basement membrane is another key step in tumor metastasis and this complex multistep process has been proved to be associated with matrix metalloproteinases (MMPs), especially MMP-2 and MMP-9." (PMID 25101278, 2014). "Known as tumor-associated macrophages (TAMs), they may sense hypoxia in tumor tissue and secrete VEGFs, basic fibroblast growth factor (bFGF), thymidine phosphorylase (TP), MMP-2, MPP-7, MPP-9 and MPP-12, and urokinase type plasminogen activator (uPA) to induce both hem- and lymphangiogenesis." (PMID 25254213, 2014). "In addition, whether the metastatic potential of primary tumor cells is associated with the expression of MMP-2 was also examined." (PMID 24690154, 2014).